GLS (glutaminase)
Diseases named in the same sentence as GLS in open-access papers (continued):
Sharing a sentence is not in itself a finding about the gene and the disease.
tumor (622 papers, 1986 to 2026). "Elevated GLS activity has been associated with tumor growth, poor prognosis, and therapy resistance." (PMID 40707944, 2025). "In this study, we found that glutamine metabolism is closely associated with DSB repair, and knocking down GLS increased tumor sensitivity to radiotherapy." (PMID 40308578, 2025). "In TNBC cell lines with dysregulation of the glutamine cleavage pathway, the loss of GLS leads to a severe inhibition of tumor growth and it is related to tumor growth, metastasis, and the immune–tumor microenvironment." (PMID 40384436, 2025). "In this regard, recent evidence reported that the inhibition of the glutaminase activity caused a reduction in tumor growth cells." (PMID 38731601, 2024). "YTHDF1, as an upstream gene of GLS, is closely associated with the reprogramming of glutamine metabolism in tumor cells." (PMID 38202722, 2023). "Estrogen can regulate the activity of various tumor-associated enzymes such as liver ribonucleases and glutaminase (GLS)." (PMID 37509133, 2023). "The same study also revealed that the activation of ATG5-mediated autophagy, which is a GLS-driven cellular response to glutamine deficiency, is an important survival strategy that endows the tumor with the ability to overcome radiation-mediated cell damage." (PMID 36499623, 2022). "Collectively, these results showed that loss of GLS in the host endothelium inhibited primary tumor growth and lung metastasis." (PMID 36381236, 2022). "Meanwhile, a large majority of cuproptosis-associated genes including FDX1, LIAS, DLD, DLAT, PDHA1, and GLS, were significantly associated with the tumor microenvironment (immune, stromal, and estimate scores) (p < 0.05)." (PMID 36105090, 2022). "The concentration of glutamine in the tumor interstitium was increased in a tumor model with specific GLS loss, and the activity of intratumoral T cells was increased." (PMID 34327138, 2021). "No specific biomarker of patient selection for GLS inhibition has been established, but studies have evaluated tumour GLS overexpression and the specific GLS1 variant that is overexpressed." (PMID 33092283, 2020). "Theoretically, GLS inhibition can limit T cell metabolism along with crippling tumour metabolism since increased glutaminolysis is a hallmark of both tumour cells and activated T cells." (PMID 33092283, 2020). "Many oncogenes and tumor suppressors have been linked to the regulation of GLS expression and glutamine metabolism." (PMID 31196962, 2019). "In either case, can we identify unique features in tumor tissue of origin or oncogene/tumor suppressor status that are associated with their dependency on glutaminase?" (PMID 31212591, 2019). "This was associated with a significant suppression of GLS activity in tumours (P=0.01130, t-test) and the expected changes in metabolites." (PMID 28671190, 2017). "We rescued the anti-tumor effect of GLS knockdown using shRNA resistant cDNAs encoding both GLS isoforms and by addition of an α-ketoglutarate (αKG) analog thus confirming the critical role of GLS in TNBC." (PMID 28950000, 2017). "GLS encodes the K-type mitochondrial glutaminase which is regulated by oncogenes and supports tumor cell growth." (PMID 29207374, 2017). "GLS1 is upregulated in cells with increased rates of proliferation, and accounts for the majority of glutaminase activity in some human tumor cells; whereas, GLS2 expression is associated with resting or quiescent cell states." (PMID 25844758, 2015). "Tumor cells (as actively proliferatingcells) or tumor microenvironment components may also leverage glutaminase toenhance glutamine metabolism, which is associated with a reduced antitumorimmune response." (PMID 40264589, 2025). "High glutaminase expression in primary patient tumor samples was associated with poor prognosis." (PMID 40943167, 2025). "Preclinical studies have suggested that patients with high GLS expression may benefit from CB-839, as GLS expression is associated with tumor dependence on glutamine." (PMID 39199642, 2024).
tumor (continued). "In TNBC, tumor cells compete for glutamine in the TME, leading to an inhibited antitumor immune response by tumor-infiltrating T lymphocytes, and in a GLS-deficient mouse model, limiting glutamine access to tumor cells restored tumor-infiltrating T lymphocyte activity." (PMID 37731509, 2023). "Finally, we found that decreased GCN5L1 levels, rather than alterations in GLS1 or GLS2 expression, are associated with human HCC tumours and support that changes in glutaminase activity are important in the pathogenesis of this disease." (PMID 35538890, 2022). "Recently, a couple of Glutaminase isoenzymes have been proven to be linked to the expression of multiple miRNAs and could potentially promote tumor development or inhibition through various miRNA-mediated pathways." (PMID 35912242, 2022). "Our data indicate that tumor GLS is inhibited by CB-839 and that the response to GLS inhibition may be dependent on how other pathways compensate for GLS loss." (PMID 36525494, 2022). "The close connection between tumour cell growth, glutamine utilisation, GLS expression, and the associated impact on T cell activation and effector function have led to targeting suppression of GLS with either small molecule inhibitors or genetic knockdown approaches." (PMID 34541580, 2021). "This study suggests that lincRNA-p21 may act as a tumor suppressor through the regulation of glutamine catabolism, which depends on GLS, although the implicated mechanisms remain unknown." (PMID 32326003, 2020). "Among these, GLS emerged as a key gene, showing low methylation levels and high mRNA expression, which were associated with poor prognosis, significant alterations in the tumor immune microenvironment, and differential sensitivity to ICIs and chemotherapeutic agents." (PMID 41348762, 2025). "Likewise, overexpression of transcription factor GRHL1 and metabolic enzyme glutaminase, both found to be identified by IHC analyses, were significantly higher in EC tissues than normal endometrium, associating these proteins with tumour proliferation and metabolic remodelling." (PMID 41312167, 2025). "Therefore, glutaminase has an important role in tumor-associated metabolic reprogramming (increased glutaminolysis) and may be related to the growth and malignancy of tumor cells." (PMID 38304027, 2023). "Additionally, studies suggest that glutaminase and mTOR inhibition causes GBM cell death and tumor inhibition in a xenograft model, resulting in an increased intracellular glutamate level and upregulation of glutaminase in GBM U87MG, and to a greater extent in U87/EGFRvIII cells." (PMID 36831355, 2023). "Previously, a tumor subtype, with high tissue oncometabolite 2-hydroxyglutarate (2HG), irrespective of hormone or growth factor receptor, was associated with stem cell-like transcriptional signature, glutaminase overexpression, poor prognosis and occurred with higher frequency in AA patients." (PMID 31428575, 2019). "High glutaminase expression in tumor tissues may be associated with poor prognosis." (PMID 28750681, 2017). "Glutaminase 1 (GLS1) drives glutaminolysis to support tumor growth and survival, yet its role in the tumor microenvironment remains poorly understood." (PMID 42070227, 2026). "Overexpression of GLS has been observed in NSCLC and is associated with increased tumor aggressiveness." (PMID 40469185, 2025). "Although clinical responses to CB-839 have been variable across tumor types, our findings suggest that MTAP-deficient tumors represent a distinct subset with heightened vulnerability to GLS inhibition." (PMID 41246302, 2025). "Dynamic monitoring techniques: Utilize positron emission tomography (PET) imaging with 11C-labeled BPTES to monitor tumor glutaminase activity in real time for guiding precision drug administration." (PMID 41041303, 2025). "In the tricarboxylic acid (TCA) cycle, glutamine undergoes deamination by glutaminase (GLS) to generate glutamate, thereby providing a carbon source for tumor cells." (PMID 41551579, 2025).
tumor (continued). "Glutaminolysis, functioning as a central metabolic pathway that sustains both energy production and redox homeostasis in tumor cells, has positioned its key enzyme glutaminase (GLS) as a promising therapeutic target." (PMID 40649322, 2025). "Glutamine (Gln) is a critical energy substrate for tumor cell proliferation, converted by GLS to α-ketoglutarate for the TCA cycle." (PMID 40990011, 2025). "Glutamine (Gln) is metabolized to glutamate by glutaminase (GLS), the rate-limiting enzyme in Gln catabolism, which is essential for tumor development." (PMID 40539068, 2025). "Overexpression of GRHL1 and glutaminase correlated with tumour proliferation and metabolic remodelling." (PMID 41312167, 2025). "For instance, glutaminase or methionine adenosyltransferase 2A deletion in mouse models enhanced T cell–mediated tumor control." (PMID 40475762, 2025). "Tumor cells avidly uptake glutamine, which is catabolized via glutaminase (GLS1) to fuel the tricarboxylic acid (TCA) cycle through anaplerotic reactions, while also generating NADPH to maintain redox homeostasis." (PMID 41253799, 2025). "Inhibiting glutaminase (GLS), the enzyme catalyzing the first step of glutaminolysis, has shown potential in suppressing tumor growth." (PMID 40214448, 2025). "Further analysis of glutamine metabolism in these two groups showed that patients with higher GLS expression in tumor cells exhibited significant differences in glutamine metabolic activity in various immune cell types." (PMID 40308578, 2025). "For example, the glutaminase (GLS) inhibitor CB839 not only delay tumor proliferation, but also enhances the therapeutic effect of chimeric antigen receptor T-cells (CAR-T)." (PMID 39925801, 2025). "Renal-type GLS is highly expressed in pancreatic ductal adenocarcinoma, and under oxidative stress conditions, tumor cells regulate the succinylation and enzymatic activity of GLS through succinyl-CoA synthetase ADP-forming subunit β (SUCLA2)." (PMID 39781339, 2025). "By contrast, CB-839 is a highly selective GLS inhibitor that has demonstrated promising therapeutic efficacy across multiple tumor models." (PMID 41179661, 2025). "EC-specific knockout of GLS, the rate-limiting deamination step in glutaminolysis, decreased tumor growth and metastasis, induced tumor blood vessel normalization, and enhanced chemotherapeutic delivery." (PMID 39567756, 2025). "Inhibition of glutaminase-1 (GLS1) in VHL-deficient renal cancers reduces aspartate synthesis and slows tumor growth." (PMID 40931345, 2025). "This suggests limited utility for [11C]glutamine PET for inferring tumor GLS activity and its specific antagonism by drug inhibitors." (PMID 40925285, 2025). "IL-16 administration improved anti-tumor immune responses by enhancing Th1 cell polarization through the inhibition of glutaminase catabolism via the down-regulation of glutaminase in CD4 + cells." (PMID 40598593, 2025). "CB‐839, a GLS inhibitor, enhances the tumoricidal activity of natural killer cells by blocking glutamine used by tumor cells, boosting glutamine availability in the TME, and activating the mTOR and c‐Myc signaling pathways." (PMID 40956032, 2025). "Treatment of TIGAR-overexpressing ESCC cell xenografts and patient-derived tumor xenografts in mice with a combination of glutaminase inhibitor and chemotherapeutic agents achieves significantly more efficacy than chemotherapy alone." (PMID 40277923, 2025). "For instance, an elevated GLS expression in tumor cells enables glutamine synthesis from glutamate, thereby permitting malignant cells to sustain proliferation even during glutamine deprivation." (PMID 39925801, 2025).
tumor (continued). "The overexpression of GLS is particularly evident in highly proliferative regions of the tumour, such as invasive margins and areas with tumour budding." (PMID 41154605, 2025). "In glutamine metabolism, glutaminase (GLS) upregulation in tumours alters immune cell activity, further enhancing immune evasion." (PMID 40175681, 2025). "Targeting glutaminolysis with inhibitors like CB-839 (telaglenastat), a glutaminase inhibitor, has been shown to inhibit tumor progression in preclinical studies by limiting the availability of key substrates for tumor cell metabolism." (PMID 40563466, 2025). "The GLS inhibitor CB-839 effectively remodels the tumor metabolic landscape, improving CAR-T cell infiltration and boosting the overall efficacy of immunotherapy." (PMID 41050070, 2025). "In BC, highly proliferative high-grade tumors, such as those in the triple negative (TN) class, have higher levels of glutamate and glutaminase (GLS) together with lower levels of Gln than low-grade tumours and normal breast epithelium." (PMID 39843491, 2025). "Pharmacological GLS inhibitors have directly targeted the apoptotic pathway, which acts as a vital role in tumor cell survival." (PMID 40956032, 2025). "Many tumours, including GBMs, overexpress the GLS isoenzymes, which correlates with malignancy, and therefore GLS isoforms have been considered prooncogenic factors." (PMID 39796278, 2025). "In the same study, glutaminase from Pseudomonas spp., in combination with azaserine enhanced the degree of tumor growth inhibition." (PMID 39905290, 2025). "Glutaminase (GLS), a pivotal gene in the regulation of glutamine catabolism, has garnered significant attention for its role in regulating tumour metabolism and copper-induced cell death." (PMID 41050056, 2025). "Recent evidence suggests that GLS, as a glutaminase, participates in tumor progression by influencing the copper death process." (PMID 40280903, 2025). "Inhibiting GLS downstream of Glu-GSH fluxes activates ROS-related signaling pathways in tumor cells, thereby promoting immunoproteasome activity to enhance tumor immunogenicity." (PMID 40598593, 2025). "The inhibition of tumor growth by targeting glutamine metabolism, particularly the Glutaminase enzyme, has been promising." (PMID 40282875, 2025). "Our in vivo pilot data further support this concept: targeting Gln catabolism with CB-839, the only clinically approved GLS inhibitor, synergized with RT to delay tumor growth in a PCa xenograft model." (PMID 40707944, 2025). "While glutaminase inhibitors have shown limited success in tumor inhibition, the aminotransferase inhibitor JHU-083 has been notably effective in reducing tumor growth in mouse models, highlighting the vital role of aminotransferases in RCC progression." (PMID 40253354, 2025). "Disrupting Gln uptake via SLC1A5, SLC7A5, or SLC38A1 depletion, or by inhibiting GLS, enhances oxidative stress and curtails DNA damage repair, thereby sensitizing tumor cells to ionizing radiation." (PMID 40707944, 2025). "Metabolic Intervention:The combination of glutaminase inhibitors like CB-839 with bisphosphonates has shown a 79% tumor inhibition rate in preclinical models by inhibiting osteoclast activity." (PMID 41458551, 2025). "Elevated MT-CO2 increases flavin adenosine dinucleotide (FAD) levels in activating lysine-specific demethylase 1 (LSD1) to epigenetically upregulate JUN transcription, consequently promoting glutaminase-1 (GLS1) and glutaminolysis for tumor cell survival." (PMID 39747079, 2025). "CB-839 targets GLS, a key enzyme in glutamine metabolism that fuels glutamate and α-ketoglutarate production essential for tumor bioenergetics and redox balance." (PMID 41246302, 2025). "Consistently, the first-in-clinic glutaminase (GLS) inhibitor CB-839, combined with RT, demonstrated a synergistic effect with radiotherapy in vivo, significantly delaying tumor growth." (PMID 40707944, 2025).
tumor (continued). "Metastatic tumor cells upregulate glutaminase (GLS), breaking down the abundant amino acid glutamine to fuel the TCA cycle and generate antioxidants." (PMID 41488002, 2025). "Glutaminase inhibition reduced colony formation and induced apoptosis in these resistant cells in vitro and decreased tumor development in vivo." (PMID 40943167, 2025). "For example, glutamine competition between glutamine-addicted breast cancer cells and anti-tumor T lymphocytes impairs T cell activity and targeting GLS in tumor cells reduced tumor growth and metastasis and improved T cell activation." (PMID 39567756, 2025). "Such metabolic interdependencies highlight the imperative for dual targeting of tumor-stromal axes, exemplified by ongoing trials combining glutaminase inhibitors (telaglenastat) with PD-L1 blockade in OXPHOS-high malignancies." (PMID 40253354, 2025). "This represents the first instance of a GLS inhibitor being applied to enhance tumor cell copper death and immunotherapy." (PMID 40598593, 2025). "Recent work demonstrates that GLS inhibitors (e.g., CB-839) reduce glutamine metabolism, depriving tumor cells of key intermediates (glutamate, α-ketoglutarate) required for anabolic growth and redox balance." (PMID 41394868, 2025). "Targeting metabolic vulnerabilities downstream of NRF2 activation by glutaminase inhibition offers dual benefits, by inhibiting tumor growth and promoting squamous differentiation, which is consistent with a less invasive phenotype." (PMID 40600748, 2025). "Tumor cells increase GLS and glutamine transporter levels, enabling tumor cells to acquire large amounts of energy and biomacromolecules through glutamine catabolism, leading to glutamine addiction in various cancer types, including myeloma and glioma." (PMID 39408814, 2024). "HOTTIP itself is targeted by tumor suppressor miRNAs, miR-192, and miRNA-240, and this regulation was shown to interfere with glutaminolysis by glutaminase GLS1 in HepG2 and SMMC7721 cells." (PMID 38203767, 2024). "We also observed elevated expression of ASCT2 and GLS in EC tumor samples, suggesting altered glutamine metabolism." (PMID 38415405, 2024). "Glutaminolysis, the process by which Gln is metabolized to produce energy, is regulated by oncogenes and tumor suppressors through the control of glutaminase (GLS) expression and activation." (PMID 38474224, 2024). "Evidence demonstrates that GLS activity correlates with tumor growth rates in vivo, and various genetic factors, such as Myc family members, are implicated in the regulation of both GLS expression and glutamine metabolism." (PMID 38731601, 2024). "Similar to glutaminase deletion, we observed that glutaminase inhibition via CB-839 significantly delayed time to tumor quintupling and increased overall survival compared to vehicle-treated mice." (PMID 38769385, 2024). "We also found increased GLS expression in the Mono 3 cluster of the involved BM relative to the distal, benign, or tumor fractions, as well as increased GLS expression in other cell types such as endothelial cells and osteoclasts." (PMID 38701369, 2024). "For example, in mTOR inhibitor-resistant glioblastoma, simultaneous inhibition of mTOR and GLS leads to a synergistic increase in tumour cell death and growth inhibition in mice." (PMID 38699532, 2024). "GLS, a key enzyme in glutamine metabolism, is highly expressed in various tumors, making it a particularly attractive target for anti-tumor therapy." (PMID 39227970, 2024). "This study suggested that combining GLS inhibition with CAD inhibition regulating de novo pyrimidine nucleotide synthesis is more efficient in inhibiting xenograft tumor growth than each monotherapy alone." (PMID 39199642, 2024). "The proliferation of tumor cells rely on glutamine, and the mitochondrial enzyme glutaminase (GLS) catalyzes the conversion of glutamine into glutamate." (PMID 38586328, 2024).